MST1 (macrophage stimulating 1)
Diseases named in the same sentence as MST1 in open-access papers (continued):
Sharing a sentence is not in itself a finding about the gene and the disease.
tumor (continued). "Notably, however, the mice born with only a single allele of Mst1 or Mst2 develop spontaneous liver tumours associated with loss of the remaining wild-type Mst1 or Mst2 allele in the tumours." (PMID 21102585, 2011). "Thus, selective upregulation of NUMB3/4 expression could be an important mechanism to reduce tumor suppressor MST1/2 activity for loss of contact inhibition of growth during the initiation and progression of cancer." (PMID 37843276, 2023). "Collectively, these data proves that EM2 mediates the activation of the Hippo signaling pathway through MST1/2, thereby exerting an anti‐tumor effect." (PMID 41144784, 2026). "We also identified the MST1 signaling being key regulator of cell death, immune function, metabolism, and tumor suppression." (PMID 41282233, 2025). "MST1/2 regulates the development of T and B cells through the “noncanonical” Hippo signaling pathway in hematopoiesis and hematopoietic tumor cells." (PMID 40573272, 2025). "Understanding how their tumor‐suppressor activities are regulated would be helpful in expanding the potential of targeting MST1/2 in the Hippo signaling pathway for cancer therapy." (PMID 40019375, 2025). "Another study reported that MST1 activation results in phosphorylation and nuclear accumulation of Foxo3a, thereby inhibiting tumour cell migration." (PMID 39413003, 2025). "In‐line with their tumor‐suppressive roles, reduced expression or activity of MST1/2 and LATS1/2 leads to metastasis in a subset of cancers." (PMID 40895190, 2025). "Studies have demonstrated that the E3 ubiquitin ligase Smurf1 can ubiquitinate MST1/2 at the K285/K282 residues, thereby promoting their degradation and diminishing their tumor-suppressive functions." (PMID 40486910, 2025). "Conversely, in aRMS, RASSF4 is upregulated by the PAX3-FOXO1 fusion oncoprotein and promotes tumor growth through MST1 inhibition and subsequent YAP activation." (PMID 41007433, 2025). "Inactivation of MST1 results in the activation of YAP target genes, which are implicated in tumor progression and metastasis." (PMID 40895190, 2025). "Upstream tumor suppressors, including MST1, LATS1/2, and FAT1/2/3/4, frequently undergo deletions or mutations, whereas downstream oncogenes such as YAP1, WWTR1, and TEAD1/2/3/4 are upregulated." (PMID 41256331, 2025). "Simultaneously, restoring the expression of tumor suppressors like LATS1/2 or MST1/2 can re‐establish normal Hippo signaling, thereby counteracting oncogenic YAP/TAZ activity." (PMID 40895190, 2025). "The dimerization of MST1/2 is a crucial step in activating the Hippo pathway and suppressing tumor growth." (PMID 39034401, 2024). "For example, MST1 is essential for the expression of MAF which has a role in cell death, inflammatory responses of tumor-associated macrophages, and macrophage differentiation (44, –, 46, 60)." (PMID 38624208, 2024). "Our previous study identified STRN3 as a key regulatory subunit recruiting MST1/2 kinases to the PP2A core enzyme and thereby causing loss of Hippo tumor suppressor signaling in GC." (PMID 38657866, 2024). "MST1 then recruits macrophages into tumor tissue and macrophage polarization to M2 type, which secrete MMP2 and MMP9 to promote HCC cell dissemination." (PMID 39695147, 2024). "The loss of MST1/MST2 has been shown to results in hyperproliferation and tumorigenesis, whereas the overexpression of MST1 prevents tumor growth and proliferation and induces apoptosis." (PMID 38444414, 2024). "Subsequently, the expression and secretion of MST1 (macrophage stimulatory protein 1) are upregulated, resulting in enhanced recruitment of macrophages into tumor tissues where they differentiate into M2-type macrophages." (PMID 39695147, 2024). "MST1, a key component of the Hippo signaling pathway known for its tumor-suppressing capabilities, emerged as a top potential binding protein and was identified as a circ_ARHGEF28-binding protein." (PMID 39034401, 2024).
tumor (continued). "YAP/TAZ pathway is key downstream component of Hippo signaling pathway, which can be activated and phosphorylated by upstream MST1/2 and LATS1/2, leading to the inhibition of function, causing cell proliferation and tumor growth." (PMID 38071381, 2023). "In both adult human and mouse pancreas, there is a broad expression of phosphorylated MST1/2, and in tumor samples from pancreatic ductal adenocarcinoma (PDAC) patients, there is a noticeable overexpression of YAP and TAZ." (PMID 37444578, 2023). "Recent research has found that inhibiting MST1/2 with its inhibitor XUM-MP-1 disrupts tumour-suppressive Hippo activity." (PMID 38201504, 2023). "By knowing that MST1/STK4 mainly functions as a tumor suppressor, while MST2/STK3 can act as an oncogene, the role of MST3/STK24 in carcinogenesis should be determined." (PMID 37181807, 2023). "As key machinery involved in the loss of the tumour-suppressive Hippo signalling pathway, STRIPAK complex-mediated MST1/2 inactivation of Hippo has been shown to facilitate DNA double-stranded break (DSB), inducing resistance to drug therapies." (PMID 38201504, 2023). "Previously, we discovered VGLL4 as a natural antagonist of YAP and dissected the machinery of PP2A-mediated inactivation of the Hippo kinases MST1/2 in tumor cells; these findings inspired us to develop therapeutic peptides to regress GC." (PMID 36921037, 2023). "Hippo signaling pathway, as a highly conserved tumor suppressor pathway, mainly included mammalian Ste20-like kinases 1/2 (MST1/2) and large tumor suppressor 1/2 (LATS1/2), YAP and/or its paralog TAZ." (PMID 36594102, 2023). "Numerous studies have reported that MST1/2 are important in cell proliferation, survival differentiation and are involved in diverse life process, including tissue homeostasis and tumour suppression." (PMID 35088536, 2022). "To this end, we performed IHC analysis of p-MST1/2 in tissue microarrays of 86 adjacent normal tissues, 94 GC tumors, and 60 tumor tissues from patients receiving oxaliplatin chemotherapy." (PMID 35290241, 2022). "Neurofibromin-2 (NF2) promotes tumor suppression in the LATS1/2 canonical hippo pathway through MST1." (PMID 35804016, 2022). "Hippo signaling is composed of tumor suppressors MST1/2 and LATS1/2, which regulate the activity of YAP/TAZ to suppress gene expression by the TF TEAD." (PMID 35017636, 2022). "High mutation frequencies were detected including KMT2C (5/5), MST1 (5/5), HLA-A (3/5) and BCL11A (3/5), which involved in modifications, tumor suppression and immune surveillance." (PMID 35504960, 2022). "It was recently reported that hydrogen peroxide inhibited tumor mortality by phosphorylating MST1, an upstream regulator of LATS1 and YAP." (PMID 35182054, 2022). "Macrophage stimulating 1 promotes the anti-tumor effects in EC via inactivating the ERK signaling pathway." (PMID 36407869, 2022). "LATS1 is a tumour suppressor which, together with MST1/2 and YAP, forms the core signalling unit (MST1/2-LATS1/2-YAP) of the MST2/Hippo pathway (herein MST2 pathway)." (PMID 35941108, 2022). "MST1 is a member of the Hippo pathway and plays an important role in cell growth, apoptosis and tissue regeneration, as well as a tumor suppressor." (PMID 34318610, 2021). "The Hippo pathway is a tumor-suppressor signaling cascade that is composed of core kinases including Macrophage Stimulating 1 or 2 (Mst1/2) and Large Tumor Suppressor 1 or 2 (LATS1/2)." (PMID 33847835, 2021). "To further confirm the requirement of Hippo kinases for RASSF2-mediated tumor suppression we generated mice with conditional gene inactivation of both MST1 (Stk4) and MST2 (Stk3) in hematopoietic cells (Vav1-Cre)." (PMID 32029705, 2020). "With regard to tumor suppressor MST1, a component of the Hippo pathway, HDAC6‐mediated deacetylation induced its degradation through chaperone‐mediated autophagy." (PMID 32755037, 2020).
tumor (continued). "Further studies are warranted to determine the tumor-suppressive properties of MST1 in GBC and its impact on patient survival." (PMID 32218280, 2020). "The core upstream components of the Hippo pathway comprise several tumour suppressors, including Mst1/2, Sav1/WW45, Lats1/2, and Mob122." (PMID 32661222, 2020). "The Hippo pathway comprises several tumor suppressors, including Mst1/2, Sav1/WW45, Lats1/2, and Mob1, which act as kinases that phosphorylate and inactivate of YAP." (PMID 32219176, 2020). "The protein levels of Rassf1, Mst1, Mst2, Sav1, Mob1, and p-Mob1 increased in the UA-treated xenograft tumor tissues as compared with those in the control tumor tissues." (PMID 31547587, 2019). "That loss of MST1 expression involving YAP has already been reported in the literature, as has the involvement of YAP in the tumour progression of MPM, yet our study was the first to identify Hippo kinase inactivation leading to YAP deregulation." (PMID 30739911, 2019). "Analysis of the Gordon dataset in Oncomine, subsequently confirmed the significantly elevated MST1 expression in tumor tissues." (PMID 30863365, 2019). "Deregulation of the mammalian Hippo signalling components has been implicated in the formation of tumours and cancers, with loss of MST1/2, LATS1/2, SAV or MOB1 resulting in the development of different tumour types in mouse models." (PMID 30139767, 2019). "MST1/2 and LATS1/2, upstream regulators of the Hippo tumor-suppressing signaling, are frequently deleted and mutated, whereas the downstream effectors, YAP and WWTR1 (encoding TAZ), are frequently amplified." (PMID 30401982, 2019). "In patient samples, MST1 mRNA was significantly elevated in the tumor specimens (n = 17) compared to benign (n = 5; p < 0.0022), with significant overexpression observed in the epithelial and biphasic subtypes." (PMID 30863365, 2019). "Then, the IHC analysis of tumor sections showed that MST1 overexpression, YAP knockdown, or VP treatment significantly decreased the expression of YAP (P < 0.01) compared with the vector samples." (PMID 31124291, 2019). "The components of Hippo pathway (Mst1/2, Lats1/2 etc.)have been reported to play tumor suppressive roles in cancers." (PMID 31703744, 2019). "The evidence shows that down-regulated MST1 expression can be a tumor growth marker of colorectal cancer or lymphoma/leukemia." (PMID 29896440, 2018). "The canonical Hippo tumor suppressor pathway in mammalian cells is primarily composed of the MST1/2-SAV1-LATS1/2-MOB1-YAP/TAZ cascade." (PMID 29577047, 2018). "MST1 is a highly conserved Ser/Thr kinase, acting as a tumor suppressor by restricting cell proliferation and survival." (PMID 29367697, 2018). "Together, this study reveals a novel mechanism whereby the AMOTp80-Merlin-MST1-LATS-YAP-BMP4 pathway leads to AMOTp80-induced tumor cell proliferation." (PMID 28052036, 2017). "The scaffold protein RASSF1A is an important tumor suppressive regulator of the Hippo kinases MST1/MST2 and the large tumor suppressor kinases LATS1/LATS2." (PMID 29179447, 2017). "The Hippo tumor suppressor pathway is essential for development and tissue growth control, encompassing a core cassette consisting of the Hippo (MST1/2), Warts (LATS1/2), and Tricornered (NDR1/2) kinases together with MOB1 as an important signaling adaptor." (PMID 28947795, 2017). "RASSF1A and RASSF5 are key bona fide tumor suppressor genes, whose protein products have been shown to regulate MST1/2 kinase activity." (PMID 27716844, 2016). "Taken together, these results indicate that Hsp27 inhibits the Hippo tumor suppressor pathway by regulating MST1 at the protein level." (PMID 27555231, 2016). "This would be supported by evidence that show that RASSF1C prevents the activation of MST1/2 dependent apoptosis and behave in some tumours as an oncogene even if it can still activate MST2 kinase activity." (PMID 27322327, 2016).
tumor (continued). "Intriguingly, recent studies have shown that most of the Hippo core tumor suppressor proteins, such as Mst1/2, Lats1/2, WW45, Mob1 are involved in regulating mitosis." (PMID 26375055, 2015). "More specifically, they showed that ILK inhibition in human tumour cells results in MST1 and LATS1 activation with concomitant inactivation of YAP/TAZ activities." (PMID 25097725, 2014). "Expression of the Mst1 gene in a NSCLC cell line suppresses tumor growth in a mouse xenograft model." (PMID 25097728, 2014). "Unfortunately, the lack of LATS1/2 animal studies has hindered the definition of how far the MST1/2-SAV-MOB1-LATS1/2-YAP axis is responsible for tumour formation in transgenic MST1/2, SAV, MOB1, or YAP mice." (PMID 25097725, 2014). "For instance, RASSF family of tumor suppressors have been shown to interact with and stabilize Mst1, thereby preventing Mst1 for the degradation and inhibiting tumor growth." (PMID 23527007, 2013). "In mammals, genetic studies provided the same picture, namely that loss of MST1/2, MOB1A/B, or LATS1 results in tumour growth, while YAP overexpression is sufficient to induce tumours." (PMID 23985307, 2013). "We and other groups have demonstrated that Mst1 and Mst2 are the most potent tumor suppressors in liver and a single copy of either Mst1 or Mst2 can significantly inhibit tumor formation in the liver." (PMID 23985272, 2013). "Does RASSF1A have additional Mst1-independent functions in the heart, as has been demonstrated in tumor cell lines ?" (PMID 22577551, 2012). "The Ras association domain family 1A (RASSF1A) tumor suppressor encodes a Sav-RASSF-Hpo domain (SARAH), which is an interaction domain characterized by hWW45 (dSAV) and MST1/2 (dHpo)." (PMID 22577552, 2012). "Lastly, we establish that increased merlin expression leads to enhanced activation of MST1/2 kinases, the mammalian homologues of Drosophila Hippo, which are established tumor suppressors and key regulators of cell proliferation and apoptosis." (PMID 22912849, 2012). "In conclusion, the present study suggests that a direct interaction between oncogenic BRAFV600E and MST1 kinase plays a crucial role in determining tumor behavior in PTC." (PMID 21249150, 2011). "The results of this study revealed that the oncogenic effect of BRAFV600E is associated with the inhibition of MST1 tumor suppressor pathways, and that the activity of RASSF1A-MST1-FoxO3 pathways determines the phenotypes of BRAFV600E tumors." (PMID 21249150, 2011). "The liver of Alb–cre Sav1 null mice show a progressive increase in Yap polypeptide greater than that seen in Mst1/Mst2 null livers, with highest levels present in the Sav1 null liver tumours." (PMID 21102585, 2011). "Ras association domain family 1A (RASSF1A), which is an important regulator of MST1 tumor suppressor pathways, is inactivated by hypermethylation of its promoter region in 20 to 32% of PTC." (PMID 21249150, 2011). "This resulted in the identification of novel cross-talksignaling between BRAFV600E and MST1, thereby demonstrating the functional activity of the RASSF1A-MST1-FoxO3 tumor suppressor system." (PMID 21249150, 2011). "In recent years, numerous studies have revealed that abnormal expression of core effectors—such as YAP/TAZ and MOB1—as well as upstream regulators (e.g., MST1/2, RASSF1A, NF2) is closely associated with patient prognosis, tumor invasiveness, and therapeutic response." (PMID 40486910, 2025). "In some cellular models such as H1299 lung cancer cells, it may inhibit Hippo pathway activity through interaction with MST1, suggesting a potential tumor activator role." (PMID 41007433, 2025). "Therefore, we reviewed RNA-seq data and found that the tumor suppressor gene Rassf1 was significantly up-regulated, and that Rassf1 enhanced Mst1/2 activity by phosphorylation." (PMID 38493147, 2024).
tumor (continued). "MST1 was related to age (P = 0.002) and tumor size (P = 0.007), YAP expression was related to gender, smoking, and grade (P = 0.033, 0.033, 0.006, respectively), SMAD3 was related to family history and grade (P = 0.004, ˂ 0.001), LATS2 was related to age (P = 0.024)." (PMID 38589525, 2024). "It is important to highlight that a combination therapy, such as dimethyl fumarate (DMF) targeting metabolite deficiency combined with an MST1 inhibitor, could potentially enhance the treatment of HCC and inhibit tumor metastasis." (PMID 39695147, 2024). "Western blotting showed that TET1 protein expression increased along with YAP1 expression in mst1/2 mutant mice tumor tissues, which suggests that TET1 expression may be regulated by YAP1 in HCC cells." (PMID 38967794, 2024). "MST1 [OR: 1.07, 95% CI: 1.04 to 1.09; PP4: 0.94] was only associated with ER-negative tumours." (PMID 38684708, 2024). "Therefore, Hippo kinase MST1/2 is recognized as a tumor suppressor gene by negatively regulating YAP/TAZ." (PMID 36757811, 2023). "Macrophage stimulating 1 (Mst1) enhances IL24-based anti-tumor via inactivating ERK-Mfn2 pathway." (PMID 37580749, 2023). "The LATS1 and MST1 were identified as tumor suppressor genes while regulating YAP phosphorylation." (PMID 37548821, 2023). "Furthermore, YAP overexpression or MST1/2 knockout in mouse liver resulted in hepatocellular carcinoma, leading to the prevalent view that Hippo signaling functions as a tumor suppressor pathway by blocking the oncogenic potential of YAP." (PMID 35654829, 2022). "While rucaparib treatment yielded modestly lower tumor weights and growth rates than did the control treatments, cotreatment of rucaparib and SHAP almost completely blocked tumor growth, suggesting that restoration or elevation of MST1/2 kinase activity can resensitize tumors to PARPi." (PMID 35290241, 2022). "Due to genomic deletions or mutations (relatively rare), epigenetic silencing, or transcriptional and post-transcriptional regulations, tumor suppressors LATS1/2 and MST1/2 could undergo loss-of-function." (PMID 33467099, 2021). "Additionally, FGFR4 drives tumor cell proliferation by inhibiting apoptosis induced by stress-related MST1/2 signaling." (PMID 34724890, 2021). "Although this work did not test if RASSF1A could be affected by bile acids, the observation serves as a proof of principle that MST1/2 can be reactivated in some tumours." (PMID 31963420, 2020). "A previous publication exhaustively characterized copy number alterations in tumors from the KP and KB1P models and showed that allele frequency of Mst1 and Mst1r genes is normal in both tumor types, without amplification or deletion." (PMID 32484599, 2020). "Interestingly, our study further revealed that the hypermethylation of MST1 promoter is associated with significantly worse OS for MPM patients, which is consistent with its tumour suppressor function and biomarker potential status." (PMID 30739911, 2019). "In contrast, Mst1 and Mst2 play a negative regulatory role in tumor proliferation." (PMID 31341493, 2019). "Importantly, activation of YAP by abrogating Hippo signaling, such as knocking out Mst1 and Mst2 in the mouse liver, has been shown to be sufficient to drive tumor formation in mice." (PMID 27589805, 2016). "The evidence we have so far indicates that the RASSF family members RASSF1A and RASSF5 (also known as NORE1 or RALP) are tumor suppressors that mediate apoptosis through different effectors including MST1/2 kinases, but their exact regulation by RASSF proteins is incompletely understood." (PMID 27716844, 2016). "Similarly, the signaling initiated by the binding of MST1 to its receptor (MST1R) is an important pathway for invasive growth in different neoplasias." (PMID 26097883, 2015).